MEIS3P1 (Meis homeobox 3 pseudogene 1)
Synonyms: MRG2; formerly MEIS3; MEIS4
Gene: Processed pseudogene on chromosome 17 (15,786,618 to 15,787,575, forward strand). Ensembl gene ENSG00000179277.
Subcellular location: Nucleus